SERPINA1 (serpin family A member 1)
Diseases named in the same sentence as SERPINA1 in open-access papers (continued):
Sharing a sentence is not in itself a finding about the gene and the disease.
asthma (38 papers, 2011 to 2025). "The presence of the PiS and PiZ variants of the SERPINA1 gene has been associated with an increased risk of asthma exacerbations." (PMID 40781310, 2025). "Among them, specific variants of the SERPINA1 gene have been recently associated with asthma exacerbations, both in the Canary Islands and other populations." (PMID 40076778, 2025). "Loss of SERPINA1 function is associated with an increased risk of lung diseases (emphysema, asthma, and chronic bronchitis) and/or liver diseases (hepatic failure, hepatitis, hepatomegaly, and cirrhosis)." (PMID 35326434, 2022). "iTRAQ-based proteomic analysis reveals that SERPINA1 is also implicated in asthma and allergic asthmatic populations sensitized to house dust mites." (PMID 35628512, 2022). "iTRAQ-based proteomic analysis reveals that SERPINA1 is also implicated in dust mite-related asthma." (PMID 35628512, 2022). "Deficient SERPINA1 phenotypes have been related to the severity of asthma in adults." (PMID 35628512, 2022). "Overall, the inflammatory effect caused by SDI exposure, together with the deregulated inflammatory response caused by specific SERPINA1 variants, could alter the microbiota abundance and composition, driving progression and exacerbations of respiratory diseases, such as asthma." (PMID 40076778, 2025). "Moreover, since Pi∗S and Pi∗Z alleles have been recently associated with asthma exacerbations, genotyping of the SERPINA1-BIE locus could also be investigated as a risk stratification tool for asthma exacerbations in the future." (PMID 40225912, 2024). "Employing shotgun proteomics, ten proteins were found significantly up-regulated in asthma, including SERPINA1; meanwhile, seven proteins were significantly downregulated in asthmatics like S100A9, S100A8, SMR3B, and SCGB1A1." (PMID 35628512, 2022). "Moreover, AAT deficiency, particularly Pi*S and Pi*Z SERPINA1 variants, has been associated with a higher risk of asthma exacerbations." (PMID 39736979, 2024). "Asthma relevant proteins that were shown to be different in asthmatics vs controls included SCGB1A1, SERPINA1, thrombins and fibrinogens." (PMID 21939520, 2011).
bronchiectasis (37 papers, 2013 to 2026). Segmental, irreversible dilation of the bronchial tree resulting in the accumulation of secretions which leads to obstruction. "Regarding respiratory complications, we observed that three of ten patients with pathogenic SERPINA1 defects developed chronic pulmonary complications; two patients developed bronchiectasis and one developed CRPD." (PMID 38791420, 2024). "The variants involved two genes associated with surfactant metabolism dysfunction (ABCA3 and CSF2RB), two with pulmonary fibrosis (MUC5B and SFTP), one with bronchiectasis (SCNN1B), and one with alpha-1-antitrypsin deficiency (SERPINA1)." (PMID 33526882, 2021).
liver cirrhosis (37 papers, 1987 to 2025). "The carriage of SERPINA1 MZ genotype increased the risk of liver cirrhosis (OR 2.57; 95% CI 1.92–3.44)." (PMID 41004464, 2025). "Our group of liver transplant candidates with liver cirrhosis of various aetiologies showed a significantly higher prevalence of unfavourable variants in the two studied genes, SERPINA1 and PNPLA3." (PMID 41004464, 2025). "The carriage of the SERPINA1 MZ genotype increased the risk of liver cirrhosis (OR 1.986; 95% CI 1.413–2.806)." (PMID 34638908, 2021). "On the other hand, the Serpin Family A Member 1 (SERPINA1 rs17580) Pi*Z-allele has been associated with liver cirrhosis, inflammatory activity and fibrosis stage." (PMID 33804385, 2021). "We conclude that both variant alleles increase the risk of liver cirrhosis in ALD and MASLD; however, SERPINA1 MZ heterozygotes have more progressive chronic liver disease and need LT at a younger age." (PMID 41004464, 2025). "More specifically, the Serpin Family A Member 1 (SERPINA1 rs17580) gene correlates with liver cirrhosis, inflammation, and fibrosis." (PMID 40004054, 2025). "Other examples of the pathogenesis of reduced SerpinA1/α1PI levels include increased neutrophil elastase in the bloodstream leading to acute inflammation, degradation of lung elasticity, and liver cirrhosis." (PMID 36335351, 2022). "As the study intended to evaluate the risk of liver cirrhosis and HCC associated with the SERPINA1 MZ or MS genotype, only these genotypes were included in further analyses, and both heterozygotes were compared with the wild-type MM homozygotes." (PMID 34638908, 2021). "PNPLA3 has not only been associated with the development of liver cirrhosis and HCC, but has also shown a stronger association when compared with other risk alleles (e.g., SERPINA1, TM6SF2, MBOAT7 or GCKR)." (PMID 33804385, 2021). "Carriage of the SERPINA1 MS genotype did not increase the risk of liver cirrhosis in any of the subgroups of the cirrhotic patients." (PMID 34638908, 2021). "Our results confirmed the postulated hypothesis about the protective effect of the carriage of MZ and MS SERPINA1 genotypes against HCC in subjects with advanced liver cirrhosis." (PMID 34638908, 2021). "Moreover, depending on the SERPINA1 defect that can lead to abnormal AAT polymerization and intracellular protein accumulation in liver, affected patients may develop liver dysfunction, eventually progressing to liver cirrhosis." (PMID 38791420, 2024). "We conclude that our results support the protective role of SERPINA1 MZ and MS genotypes against HCC in liver cirrhosis." (PMID 34638908, 2021).
liver fibrosis (32 papers, 2012 to 2026). "Liver-directed gene transfer of TFEB attenuated hepatic fibrosis by accelerating the autophagy-dependent degradation of SERPINA1 polymer in autolysosomes and decreasing SERPINA1 monomer expression in SERPINA1 deficient mice." (PMID 32724454, 2020). "This raises the possibility that mRNA-encoded SerpinA1 protein, when expressed in the liver, could decrease hepatic production of the PIZZ form and subsequently inhibit hepatic fibrosis." (PMID 30009048, 2018). "For instance, the SERPINA1 gene with genotypes MZ and MS, in this case, represents a protective factor for the development of fibrosis, whereas, for example, the polymorphism of the PNPLA3 rs738409 C > G gene is a risk factor for both liver fibrosis and the development of HCC." (PMID 36013566, 2022).
colorectal cancer (30 papers, 2013 to 2026). A primary or metastatic malignant neoplasm that affects the colon or rectum. "Receiver operating characteristic (ROC) curve showed diagnostic accuracy of peripheral blood SERPINA1 expression in discriminating colorectal cancer patients from healthy population, with area under the curve (AUC) of 0.74 and 0.76, respectively." (PMID 38710698, 2024). "Moreover, we confirmed that SERPINA1 expression was significantly associated with clinical features in seven digestive cancers, similar to a paper proving that different SERPINA1 levels exist in patients with varying characteristics in colorectal cancer." (PMID 37511325, 2023). "Given the association between HIV infection and poorer prognosis in colorectal cancer (CRC), coupled with the reports of reduced survival in CRC patients exhibiting lower SERPINA1 expression, we conducted IHC analysis to verify SERPINA1 protein levels." (PMID 41584047, 2026). "Our study identified SERPINA1 as a colorectal cancer liver metastasis-related gene by analyzing the sequencing data." (PMID 38710698, 2024). "log(P/(1-P) = -7.8709 + 4.5956 × IGFBP2 + 0.2732 × ITIH3 + 0.0909 × LRG1 + 0.1015 × C9 -3.2205 × CNDP1 + 0.0239 × ORM1 + 0.0811 × SERPINA1, where P is a value between 0 and 1 that represents the probability of the event (colorectal cancer)." (PMID 38383428, 2024). "Further, the relationship between SERPINA1 and colorectal cancer liver metastasis was investigated through in vivo model." (PMID 38710698, 2024). "In summary, we found that SERPINA1 can promote the proliferation, migration, and liver metastasis of colorectal cancer and plays a key role in the progression of colorectal cancer." (PMID 38710698, 2024). "The autophagy-related gene SERPINA1 has been demonstrated to affect the invasive and metastatic capabilities in colorectal cancer." (PMID 38555418, 2024). "Previously, it was described that SERPINA1 overexpression was also observed in cutaneous melanoma, pancreatic ductal adenocarcinoma, colorectal cancer, and non-small-cell lung cancer (NSCLC)." (PMID 39851465, 2024). "Through colony formation, EDU and MTS assays, we verified that SERPINA1 promoted the migration and invasion of colorectal cancer." (PMID 38710698, 2024). "We recently identified an RNA-sequencing profile that associates with CAT in colorectal cancer (CRC) patients, with REG4, SPINK4, and SERPINA1 as the top-3 upregulated genes at mRNA level." (PMID 38066386, 2024). "A report published in 2015 presented that Snail and SERPINA1 promote tumor progression in colorectal cancer." (PMID 38069324, 2023). "In colorectal cancer, expression of SERPINA1 was positively correlated to survival, stage, N, furthermore Snail and SERPINA1 have been demonstrated to promote colorectal cancer progression through fibronectin." (PMID 34315829, 2021). "In this study, we investigated the role of Snail and serpinA1 in colorectal cancer (CRC) and examined the mechanisms through which these proteins mediate CRC progression." (PMID 26015410, 2015). "Moreover, an increase in SERPINA1 was related to advanced stage and poor prognosis of colorectal cancer, being considered a reliable prognostic biomarker and therapeutic target in colorectal cancer." (PMID 40236629, 2025). "The role of SERPINA1 in colorectal cancer (CRC) progression remains controversial." (PMID 41425595, 2025). "We established stable colorectal cancer cell lines with SERPINA1 overexpression and knockdown." (PMID 38710698, 2024). "In addition, our study found that after increasing the expression of SERPINA1 in colorectal cancer cells, the expression of c-myc also increased significantly." (PMID 38710698, 2024). "Additionally, GSE164191 and GSE10715 datasets showed that the peripheral blood mRNA levels of SERPINA1 in colorectal cancer patients was higher than that in healthy population." (PMID 38710698, 2024). "Previous study found that SERPINA1 was related to the early diagnosis of colorectal cancer." (PMID 38710698, 2024).
colorectal cancer (continued). "To further verify the regulatory relationship between CEBPB and SERPINA1 and their effects on colorectal cancer proliferation, we transfected RKO and Caco2 cells with si-NC and Control, si-CEBPB and Control, and si-CEBPB and SERPINA1, respectively, and performed colony formation assays." (PMID 38710698, 2024). "Transwell experiment results showed that SERPINA1 overexpression could promote the migration and invasion ability of colorectal cancer cells (P < 0.01)." (PMID 38710698, 2024). "Despite analyzing the activation of the colorectal cancer JAK1-STAT3 pathway by SERPINA1 expression through multidimensional prediction and experimental validation, the mechanistic insights into how SERPINA1 upregulation results in JAK1 phosphorylation remain to be explored." (PMID 38710698, 2024). "In addition, through Transwell and wound healing assays, we confirmed that SERPINA1 promoted the migration and invasion of colorectal cancer." (PMID 38710698, 2024). "Another interesting example is mutation of the ER-to-Golgi trafficking protein LMAN1 in colorectal cancers, which causes reduced secretion of the LMAN1 client protein α-1-antitrypsin (A1AT; also known as SERPINA1), an angiogenesis inhibitor, thereby contributing to tumour blood supply and growth." (PMID 32433026, 2020). "Serpina1 is the upregulated protein in this group which has a positive prognostic significance in colorectal cancer, and this could result, at least partly, from its function of PTEN stabilization, and/or negative regulation of PI3K/AKT network." (PMID 32973493, 2020). "For instance, in colorectal cancer (CRC), C/EBPβ regulates the transcription of serpin family A member 1 (SERPINA1), thereby promoting migration through the activation of STAT3 signaling." (PMID 39858431, 2024). "Based on the colorectal cancer dataset GSE19860, Spearman’s method was used to analyze the correlation between SERPINA1 and FOXA1 (r = 0.19, P = 0.23) and the correlation between SERPINA1 and CEBPB (r = 0.45, P = 0.0034)." (PMID 38710698, 2024). "Based on data from public datasets, the transcription factor CEBPB is more valuable than FOXA1 in evaluating the prognosis of colorectal cancer, so we further explored the regulatory relationship between CEBPB and SERPINA1." (PMID 38710698, 2024). "Previous reports showed that SERPINA1 and SERPINA3 are potential prognostic markers and therapeutic targets for colorectal cancer and melanoma, respectively." (PMID 31620367, 2019). "The results suggest that SERPINA1 and CEBPB are positively correlated in colorectal cancer." (PMID 38710698, 2024). "The Venn diagram shows that SERPINA1 is the only intersection the top 50 differentially expressed genes between GSE49355 and RKO-H/RKO cell groups as well as between Caco2-H/Caco2 cell groups, suggesting that SERPINA1 plays an important role in colorectal cancer liver metastasis." (PMID 38710698, 2024).
Obesity (26 papers, 2012 to 2026). Accumulation of substantial excess body fat. "Conversely, SerpinA1 knockout mice exhibit decreased adipocyte mitochondrial function, impaired thermogenesis, obesity, and systemic insulin resistance." (PMID 39532838, 2024). "As a result, higher levels of SerpinA1 promote energy expenditure and improve obesity and glucose metabolism in mice." (PMID 39532838, 2024). "Thus, in vivo, SerpinA1 activates BAT and promotes browning of WAT to prevent obesity, increase energy expenditure and improve glucose tolerance, whereas the knockout of SerpinA1 does the converse." (PMID 39532838, 2024). "Thus far, there are few reports regarding potential effects of SerpinA1 on metabolism, although SerpinA1 has been shown to inhibit obesity-induced neutrophil elastase and improve insulin sensitivity." (PMID 39532838, 2024). "An imbalance between SERPINA1 and neutrophil elastase might contribute to the development of obesity and related inflammation, insulin resistance, and liver steatosis." (PMID 34501327, 2021). "Conversely, SerpinA1 knockout (SPA1KO) mice show adipocyte mitochondrial dysfunction, obesity, energy expenditure impairment, and hyperglycemia with systemic insulin resistance." (PMID 39532838, 2024). "Here, the authors show that SerpinA1, secreted from the liver, activates mitochondrial UCP1 expression through interaction with EphB2 in adipocytes, contributing to increased energy expenditure, improved glucose metabolism and reduced obesity." (PMID 39532838, 2024). "SERPINA1, which may serve as an important molecular marker of obesity, affects energy expenditure by regulating the AMPK pathway and promotes the development of obesity-related metabolic complications." (PMID 36873932, 2023).
Wilson disease (26 papers, 2008 to 2025). A very rare inherited multisystemic disease presenting non-specific neurological, hepatic, psychiatric or osseo-muscular manifestations due to excessive copper deposition in the body. "Other studies on the development of HCC have shown that it leads to changes in hemochromatosis, α1‐antitrypsin deficiency (SERPINA1), glycogen storage disease (G6PC, SLC37A4), tyrosinemia (FAH), porphyria (HMBS, UROD), and Wilson disease (ATP7B)." (PMID 41201177, 2025).
rheumatoid arthritis (22 papers, 2007 to 2026). A chronic, systemic autoimmune disorder characterized by inflammation in the synovial membranes and articular surfaces. "The rs28929474 polymorphism near SERPINA1 increases susceptibly to childhood asthma and was previously noted to contribute to the shared genetic relationship between rheumatoid arthritis and osteoporosis." (PMID 38785970, 2024). "As early phase proteins, it is perhaps unsurprising that levels of SerpinA1 and SerpinA3 have been shown to be increased in the serum and synovial fluid of rheumatoid arthritis patients and SerpinA1 expression is increased in response to inflammatory cytokines in chondrocytes." (PMID 33843993, 2021).
type 1 diabetes (20 papers, 2014 to 2025). "Several studies indicated increased levels of alpha-1-antitrypsin in the serum of diabetic subjects, while others showed in fact decreased serum concentrations of SERPINA1 and increased plasma levels in insulin dependent diabetes." (PMID 36080270, 2022).
viral infection (20 papers, 2010 to 2025). "This study broadens the relationship between the serine protease inhibitor family and GCRV infection in grass carp and analyzes the possible mechanisms through which SERPINA1 suppresses viral infection in vivo." (PMID 36159797, 2022). "SERPINA1, a member of the serine protease inhibitor family, plays a role in viral infection and inflammation by regulating the activities of serine and cysteine proteases." (PMID 36159797, 2022). "This study proposes that SERPINA1 can inhibit viral infection through interaction with the coagulation factor, providing new insights into the molecular mechanism of SERPINA1’s antiviral function." (PMID 36159797, 2022). "Subsequently, in order to explore the dynamic expression pattern of du SERPINA1 in ducks during viral infection, the du SERPINA1 mRNA expression after DHV-1 or poly I: C challenge was detected." (PMID 31016183, 2019). "To conclude, our results provide a better understanding of du SERPINA1 function in immunity during viral infection." (PMID 31016183, 2019). "During the process of viral infection, SERPINA1 inhibits HIV-1 replication in U1 monocytes." (PMID 36159797, 2022). "However, the expression and function of SERPINA1 gene in immune defense against viral infection remain unknown in ducks." (PMID 31016183, 2019). "SERPINA1 directly interacts with the gp41 protein of HIV and thus inhibits its binding to the host CD4 co-receptor; thereby, inhibiting viral infection." (PMID 36159797, 2022). "During viral infection or inflammation, MMP25 inactivates alpha-1 proteinase inhibitor (SERPINA1), the major tissue protectant against proteolytic enzymes released by active neutrophils, thus promoting the migration of neutrophils to sites of active inflammation." (PMID 37036007, 2023).
gastric cancer (18 papers, 2008 to 2025). A primary or metastatic malignant neoplasm involving the stomach. "Previous studies have reported that strong expression of SERPINA1 is associated with poor prognosis in patients with lung and stomach cancer." (PMID 34707986, 2021). "Enhanced SERPINA1 expression is significantly associated with invasion and metastasis in gastric cancer." (PMID 28678795, 2017). "Elevated expression of SERPINA1 has been associated with the advanced stage, lymph node metastasis, poor prognosis and shorter overall survival in CRC and gastric cancer." (PMID 32503434, 2020). "In a previous study, we found that Snail regulates the expression of serpinA1 and is involved in gastric cancer progression." (PMID 26015410, 2015). "We have also reported that serpin peptidase inhibitor clade A member 1 (serpinA1) is a direct target of Snail in gastric cancer cells." (PMID 26015410, 2015). "We previously reported that Snail regulates serpinA1 by binding to its promoter in gastric cancer." (PMID 26015410, 2015).
Hypertension (18 papers, 2012 to 2025). The presence of chronic increased pressure in the systemic arterial system. "SERPINA1 in urine has been associated with the most severe forms of preeclampsia (p = 0.014), in terms of systolic hypertension (p = 0.01) and proteinuria (p = 0.006)." (PMID 32019243, 2020). "The increase in SERPINA1 excretion has been reported in patients with arterial hypertension." (PMID 25946105, 2015).